CXCL12 (C-X-C motif chemokine ligand 12)
Diseases named in the same sentence as CXCL12 in open-access papers (continued):
Sharing a sentence is not in itself a finding about the gene and the disease.
pancreatic cancer (continued). "Additionally, it has been previously demonstrated that CXCL12 expression suppresses pancreatic cancer growth and metastasis." (PMID 28178311, 2017). "Thus, AMD3100 attenuated successfully CXCL12-induced chemotaxis, cell motility, and proliferation, as well as resistance to gemcitabine in pancreatic cancer cell lines." (PMID 26091099, 2015). "Moreover, a previous report showed that CXCL12-induced sonic hedgehog expression depends on ERK activation in pancreatic cancer cells." (PMID 25121739, 2014). "In vivo roles for the CXCR4 ligand CXCL12 in pancreatic cancer malignancy were investigated." (PMID 24594697, 2014). "The chemotactic interaction between CXCR4 and its ligand CXCL12 may be a critical event during the progression of pancreatic cancer." (PMID 23181100, 2012). "First, we verified that CXCL12 induces an increase in phospho-ERK in pancreatic cancer cell lines." (PMID 22319600, 2012). "Chemokine CXCL12 is characteristically expressed in select tissues, but may also be expressed via an autocrine feedback loop mechanism in pancreatic cancer cells." (PMID 22472349, 2012). "In conclusion, our data suggest that the chemotactic interaction between CXCR4 and its ligand CXCL12 may be a critical event in the progression of pancreatic cancer." (PMID 23181100, 2012). "As a result, we examined CXCL12 activity in pancreatic cancer cell lines." (PMID 22472349, 2012). "Our previous investigations have implicated chemokine receptor CXCR4 and its selective ligand CXCL12 in the pathogenesis and progression of pancreatic intraepithelial neoplasia and invasive pancreatic cancer; hence, CXCR4 is a promising target for suppression of pancreatic cancer growth." (PMID 22319600, 2012). "Hence our study suggests that efforts to therapeutically target CXCL12 signaling in pancreatic cancer should be focused at the level of the ligand to account for both CXCR4 and CXCR7 activity." (PMID 22472349, 2012). "First, our results suggest that CXCL12 promotes anti-apoptosis in pancreatic cancer cells." (PMID 22319600, 2012). "The interaction between CXCR4 and CXCL12 may play crucial roles in the metastasis and progression of pancreatic cancer by its effects on the formation of new blood vessels and lymphatic vessels." (PMID 23181100, 2012). "In EOC, CXCL12 mRNA and protein have been detected mostly in the tumor cells themselves, and this feature has been reported for other cancers, including follicular lymphoma, pancreatic cancer, glioma and astrocytoma." (PMID 21410972, 2011). "AMD3100 arrested the CXCL12-induced pancreatic cancer cell growth and drug resistance." (PMID 21045835, 2010). "Next, we examined whether CXCL12-induced chemoresistance was due to its antiapoptotic effects on pancreatic cancer cells, DNA fragmentation and decreased caspase." (PMID 21045835, 2010). "Our results also indicate that the CXCL12-induced gemcitabine resistance in pancreatic cancer cells might, in part, also be due to the activation of NF-κB and induction of downstream survival proteins (Bcl-2, Bcl-xL, survivin, and so on)." (PMID 21045835, 2010). "Therefore, we examined the transcriptional activities of β-catenin and NF-κB responsive promoters after CXCL12 treatment in pancreatic cancer cells." (PMID 21045835, 2010). "Having observed a role of CXCR4 activation in gemcitabine resistance and potentiation of survival pathways, we investigated if the small-molecule CXCR4 antagonist, AMD3100, could diminish CXCL12-induced chemoresistance in pancreatic cancer cells." (PMID 21045835, 2010). "Both studies concluded that TN14003 was a very effective inhibitor of the CXCR4/CXCL12 chemokine axis, and may be a possible future therapy for breast and pancreatic cancer." (PMID 18001467, 2007).
pancreatic cancer (continued). "A study found that increased expression of CXCL12 by pancreatic cancer cells limited the infiltration of cytotoxic T cells, thus promoting the protumor response, with another group suggesting some cancer cells in pancreatic cancer-bearing mice evade T-mediated attack by reducing CXCL12 expression." (PMID 38786066, 2024). "These perivascular immunosuppressive macrophages and myeloid-derived suppressor cells could also be recruited by chemokine CXCL12 and granulocyte-macrophage colony-stimulating factor (GM-CSF) induced by pancreatic cancer cells treated with paclitaxel and gemcitabine/5-FU, respectively." (PMID 37173915, 2023). "Moreover, CXCL12 predicted short RFS (p = 0.0001) (n = 48, PFS data were unavailable for 3/51 R0 patients) and CSS (p = 0.017) (n = 50, as 1 out of 51 R0 died from other cause than pancreatic cancer) in R0 patient’s subgroup." (PMID 36359736, 2022). "Interestingly, the central roles of Nqo1, Aox1, and Cxcl12 are demonstrated in pancreatic cancer." (PMID 35180880, 2022). "Although CXCL12 seems to promote tumor invasion, proliferation, angiogenesis, epithelial to mesenchymal transition and metastasis in pancreatic cancer, its roles seem to be pleiotropic, and this could be due to the presence of at least six CXCL12 splicing isoforms, each with different roles." (PMID 34282405, 2021). "Therefore, we examined the change in BAD phosphorylation in CXCL12-treated pancreatic cancer cells." (PMID 21045835, 2010). "In pancreatic cancer, iCAFs also show high Lamin A/C and pro-inflammatory cytokines such as IL-6, IL-8, CXCL1, and CXCL12." (PMID 40846900, 2025). "CXCL12, also known as stromal cell-derived factor 1 (SDF1), is an ELR− CXC chemokine and one of the most widely researched and targeted chemokines in pancreatic cancer." (PMID 38339310, 2024). "CXCR4 is the predominant receptor for the chemokine ligand CXCL12; overexpression of CXCR4 and CXCL12 is found in several solid cancers, such as CRC, gastric cancer, pancreatic cancer and lung cancer." (PMID 38791414, 2024). "Co-cultivation experiments involving ovarian, colorectal, and pancreatic cancer cells with CAFs or CAF supernatants have demonstrated a reduction in cisplatin- and gemcitabine-induced apoptosis, attributed to CAF-derived CXCL12." (PMID 38818409, 2024). "The increased level of CXCR4 and its canonical ligand CXCL12 (SDF-1α) is frequently found to be elevated in metastatic sites of many cancers, including breast cancer, pancreatic cancer, or cervical/ovarian carcinoma." (PMID 37853467, 2023). "CAFs increase the expression of PD-L1 in pancreatic cancer by secreting CXCL5 and CXCL12 via phosphatidylinositol-3-kinase/protein kinase B signaling pathway, thus promoting the formation of immunosuppressive microenvironment." (PMID 37064113, 2023). "Pancreatic cancer cells secret of various cytokines (such as IL-10, TGF-B and IL-23) and chemokines (such as CXCL1-3, CXCL5, CXCL12, CCI2 and VEGF) to enhance the activation of stromal cells and the accumulation of immunosuppressive cells." (PMID 37064113, 2023). "In a mouse model of pancreatic cancer, FAP+ CAFs are the main source of CXCL12 that combines with CXCR4 on the surface of cancer cells and marginalized T cells through a CXCL12–CXCR4 signaling mechanism, leading to tumor immunosuppression." (PMID 37143134, 2023). "For instance, targeting CAFs-derived CXCL12 with the administration of AMD3100, the inhibitor of the CXCL12 receptor, revealed the antitumor effects in pancreatic cancer." (PMID 36671447, 2022). "In the pancreatic cancer microenvironment, FAP-expressing CAFs have been a major source of CXCL12, which can bind to KRT19 (cytokeratin 19) at the surface of pancreatic cancer cells." (PMID 35805064, 2022). "For example, the CXCL12/CXCR4 axis is involved in tumor growth, invasion, angiogenesis, and metastasis in CRC, breast and pancreatic cancers." (PMID 36703779, 2022).
pancreatic cancer (continued). "The CXCR4/CXCL12 axis seems to play an important role in the desmoplastic reaction characterizing PDAC, while CXCR3/CXCL10 resulted expressed in pancreatic tumor tissue, and their presence has been correlated with poor prognosis." (PMID 36142575, 2022). "For example, CXCL12/CXCR7 can activate Rho/ROCK pathway and promote the migration and invasion of pancreatic cancer cells; CXCL12/CXCR7 promotes the malignancy of renal cancer cells by activating mTOR signaling pathway." (PMID 35226830, 2022). "PAK4/LIMK1 signaling mediates the chemoprotective action of CXCL12/CXCR4, and the inhibition of PAK4 leads to re-sensitization of pancreatic cancer cells to DTX-induced cellular toxicity even in the presence of CXCL12." (PMID 36230657, 2022). "For example, CXCL12/CXCR4 axis advanced the invasion and metastasis of pancreatic cancer through complex crosstalk with other pathways, and was correlated with the poor prognosis of patients." (PMID 36419891, 2022). "ONCOMINE data showed that in addition to CXCL1, CXCL4, CXCL11 and CXCL12, the mRNA levels of the other 12 CXC chemokines were significantly increased in pancreatic cancer." (PMID 35468838, 2022). "Although the treatment with LDE225 attenuates pancreatic cancer growth in KPC mice, LDE225 increases chemokine Cxcl12 expression, reduces CD8-positive T cells, and increases regulatory T cell (Treg) immunosuppression." (PMID 35159011, 2022). "CXCL12, also known as stromal cell-derived factor 1 (SDF1), is a major ligand for CXCR4, and the CXCL12–CXCR4 axis promotes pancreatic cancer development, invasion, and metastasis." (PMID 36010986, 2022). "In CXCL12-treated pancreatic cancer cells, CXCR4 antagonist AMD3100 does not inhibit migration and invasion, indicating CXCR7 promotes pancreatic cancer cell migration and invasion." (PMID 35159011, 2022). "CAFs are also the primary source of CXCL12, which interacts with the receptor CXCR4 to stimulate pancreatic cancer cell proliferation, regulating the infiltration of CTLs and the recruitment of Tregs." (PMID 36284271, 2022). "SDF-1, also named CXCL12, is a mediator of tumor–stromal interactions in different cancer types, including lung and pancreatic cancer, via the CXCR4/CXCL12 axis." (PMID 33673405, 2021). "According to the literature, the expression of the FAP, CXCL12, CTGF, and SNAI1 genes is characteristic of CAFs in the TME of pancreatic cancer." (PMID 33804861, 2021). "For instance, IGF-1 activates the IGF-1R/AKT/mTOR survival pathway in CRC, and CXCL-12 promotes EMT and invasion in pancreatic cancer." (PMID 33553157, 2020). "The iCAF subpopulation is detected in invasive pancreatic cancer, and iCAFs exhibit elevated expression of VIM, FAP, COL3A1, DES, IL6, and CXCL12 and reduced expression of ACTA2 (coding α-SMA)." (PMID 33333727, 2020). "Il6, Ccl2, Ccl7, Cxcl12, and Pgdfra are expressed in FB1 subtype fibroblasts in the normal pancreas, as well as during the progression of pancreatic cancer." (PMID 33333727, 2020). "CAFs from different cancer types also express high levels of SDF-1/CXCL12, including breast, endometrial and pancreatic cancer." (PMID 31861782, 2019). "In a murine model of pancreatic cancer, CAF-derived CXCL12 protected tumor cells from T cell accumulation." (PMID 31428105, 2019). "The CXCL12/CXCR4 axis seems to play an important role in the processes of invasion, proliferation, migration, metastasis, and angiogenesis in pancreatic cancer." (PMID 31275385, 2019). "C-X-C motif chemokine ligand 12 (CXCL12) was found to be the chemokine responsible for recruiting effector T cells, and targeting its receptor (CXCR4) resulted in reduced pancreatic tumor growth in a T-cell-dependent manner." (PMID 29301364, 2018). "In line with this, it was recently proposed that stimulation of ACKR3 with CXCL12 leads to the activation of mTOR and Rho/ROCK pathways promoting cell migration and liver metastasis of pancreatic cancer cells." (PMID 29156704, 2017).
pancreatic cancer (continued). "The chemokine CXCL12 binds the two receptors CXCR4 and CXCR7 and transduces on the mTOR pathway in pancreatic cancer, gastric cancer, T cell leukemia cell and in human renal cancer cells." (PMID 26934559, 2016). "It has been reported that CXCL12/CXCR4 expression was significantly correlated with microvascular density (MVD)/microlymphatic vessel density (MLVD), and thus might be associated with angiogenesis/lymphangiogenesis and organ-specific metastasis in pancreatic cancer." (PMID 25679210, 2015). "This study reports the influence of CXCL12 and its receptor CXCR4 on the progression of pancreatic cancer and highlights the correlation between the CXCL12/CXCR4 axis and the organ-specific metastasis of pancreatic adenocarcinoma (PAC)." (PMID 23181100, 2012). "First, we discovered that pancreatic cancer cells co-expressing CXCR4/CXCR7 had increased levels of ERK phosphorylation and K-Ras activity when exposed to CXCL12." (PMID 22472349, 2012). "The paratumorous vessels and neural tissue with positive CXCL12 and CXCR4 expression were invaded by CXCL12-positive pancreatic cancer cells." (PMID 23181100, 2012). "For example, integrin-mediated pancreatic cancer cell migration at LN was found to up-regulate CXCR4 and IL-8 expression and responsiveness to CXCL12 stimulation." (PMID 22253872, 2012). "To directly assess the role of K-Ras in CXCL12 signaling, we knocked down KRAS using siRNA and then exposed pancreatic cancer cell lines to CXCL12." (PMID 22472349, 2012). "Next, we observed consistent increases in ERK1/2 phosphorylation after exposure to CXCL12 or CXCL11, a CXCR7 agonist, in pancreatic cancer cell lines co-expressing CXCR4/CXCR7." (PMID 22472349, 2012). "We observed that all the pancreatic cancer cell lines tested expressed CXCR4, but low levels of CXCL12." (PMID 21045835, 2010). "CXCL12, a ligand for CXCR4, is also abundantly produced by neighbouring stromal cells and activation of CXCR4-expressing pancreatic cancer cells by CXCL12 leads to enhanced chemotaxis, transendothelial migration, and Matrigel invasion." (PMID 21045835, 2010). "Our data show that all pancreatic cancer cell lines examined express CXCR4 and low levels of CXCL12 (13–230 pg per ml per 106 cells)." (PMID 21045835, 2010). "Pancreatic cancer cells were treated for 1 h with AMD3100, LY294002, and PD98059 before treatment with CXCL12 alone or in combination with gemcitabine." (PMID 21045835, 2010). "While CXCL12 mRNA is expressed in pancreatic cancer tissues, CXCR4 mRNA is expressed both in pancreatic cancer tissues and in pancreatic cancer cell lines (AsPC-1, BxPC-3, CFPAC-1, HPAC and PANC-1)." (PMID 19787093, 2008). "We conducted a scientific literature search on Pubmed and Google Scholar including retrospective, prospective studies and reviews focused on the current research elucidating the emerging role of CXCL12 and its receptors CXCR4 – CXCR7 in the pathogenesis of pancreatic cancer." (PMID 37035150, 2023). "Further evidence for the role of CXCL12 in T-cell infiltration came from other preclinical studies, where inhibition of CXCR4 (the receptor for CXCL12) enhanced the response to checkpoint inhibition in a pancreatic cancer model." (PMID 35814453, 2022). "CAFs alter the pancreatic cancer microenvironment by the secretion of growth factors such as C-X-C motif chemokine ligand 1 (CXCL1), CXCL12, C-C motif chemokine ligand 8 (CCL8), stromal cell-derived factor-1 (SDF-1), IL-6, IL-11, VEGF and others." (PMID 35883598, 2022). "Mouse pancreatic cancer cells without the CXCL12 coating formed tumors that did not exclude T cells and responded to anti–PD-1 antibody treatment." (PMID 35046049, 2022). "Anti-CXCL12 (NOX-A12) combined with pembrolizumab can prolong the time on trial treatment compared with their last standard treatment and activate the Th1 immune response in patients with metastatic colorectal and pancreatic cancer." (PMID 35468838, 2022).
pancreatic cancer (continued). "In pancreatic cancer, where CXCR4 and CXCR7 receptors are commonly co-expressed on tumor cells, blocking or depleting CXCL12 may be a more effective strategy." (PMID 35008248, 2021). "CXCL12 can induce MMP-2 and MMP-9 upregulation in pancreatic cancer cells." (PMID 33363463, 2020). "Interestingly, when the expression of Gαi2 was suppressed in human pancreatic cancer cell line PANC-1, ELMO2 translocation was substantially reduced, even in the presence of CXCL12 stimulation." (PMID 32292657, 2020). "While the NF-κB pathway induces the upregulated expression of some chemokines such as CCL2, CCL5, CXCL5, CXCL8, CXCL10, CXCL12, and CX3CL1, it also participates in the antiapoptotic and proliferative effects of CCL5, CCL20, CXCL8, and CXCL12 in pancreatic cancer." (PMID 31991604, 2020). "Forming a paracrine loop of the VEGF-mediated expression of CXCR4 by endothelial cells and the CXCL12-induced expression of VEGF by endothelial cells, this pathway is believed to assist in pancreatic cancer progression by inducing angiogenesis and lymphangiogenesis." (PMID 32069809, 2020). "Indeed, both pancreatic cancer cells and tissues highly expressed CXCR4 and ACKR3 receptors on their surface, which are activated by CAFs-released CXCL12 chemokine." (PMID 31275385, 2019). "In a pancreatic cancer in vivo mouse model, cells producing CXCL12 showed deficits in migration and poor metastatic potential in comparison to control cells producing no CXCL12." (PMID 30175096, 2018). "In pancreatic cancer, conflicting and incomplete reports suggest either that CXCL12 expression is elevated or that CXCL12 is not expressed in the vast majority of patients." (PMID 24594697, 2014). "Our results are consistent with published reports which show that not all pancreatic cancer cell lines respond to CXCL12 with increased proliferation; the mechanism responsible for this has not yet been elucidated." (PMID 22319600, 2012). "Therefore, in our study, we evaluated the expression of CXCL12/CXCR4 and found a critical relationship between CXCL12/CXCR4 and tumor stage and grade in pancreatic cancer." (PMID 23181100, 2012). "No definitive correlation was observed between CXCL12 expression and progression of pancreatic cancer." (PMID 23181100, 2012). "Since quinacrine did not suppress CXCL12-mediated calcium flux, it was omitted from further analysis in pancreatic cancer cell lines." (PMID 22319600, 2012). "This hypothesis is supported by findings that the expression pattern of CXCL12 and CXCR4 in pancreatic cancer tissue significantly correlated to clinicopathological features." (PMID 23181100, 2012). "To date, the clinical significance of the CXCL12/CXCR4 axis in pancreatic cancer has not yet been clearly elucidated." (PMID 23181100, 2012). "Our data showed an increased level of phospho-BAD in both Panc1 and MiaPaCa cell lines treated with CXCL12, suggesting that it could be one of the mechanisms by which CXCL12–CXCR4 signalling axis protects the pancreatic cancer cells from apoptosis." (PMID 21045835, 2010). "In the absence of serum growth factors, CXCL12 stimulation led to the 29–33% induction of growth in pancreatic cancer cells, whereas a moderate increase (11–13%) was observed in the presence of serum growth factors." (PMID 21045835, 2010). "We treated pancreatic cancer cells (Panc1 and MiaPaCa) with various doses of gemcitabine (0–10 μM) in the presence and absence of CXCL12 (100 ng ml−1) in serum-containing media." (PMID 21045835, 2010). "Thus, it suggests that the interaction between CXCL12 and CXCR4 is relevant to pancreatic cancer cell progression and metastasis." (PMID 19787093, 2008). "In addition, the low expression of RHBDD2 in supporting cells, specifically fibroblasts, of clinical pancreatic cancer showed a shortened prognosis, and a negative correlation with CXCL12 was observed." (PMID 37264057, 2023).